IL6 (interleukin 6)
Diseases named in the same sentence as IL6 in open-access papers (continued):
Sharing a sentence is not in itself a finding about the gene and the disease.
Hypertension (continued). "In the current study, the average values of CRP, IL-6 and TNF-α in patients with chronic TAAD and hypertension tended to be higher than those in the healthy controls (Chronic TAAD vs. Healthy, P = 0.06; uHT vs. Healthy, P = 0.09)." (PMID 25592634, 2015). "The ischemic placenta induces activation of peripheral T cells, which can directly promote the development of hypertension by production of cytokines such as TNF-α and IL-6 and the anti-angiogenic factor sFlt-1 and by stimulating B cells to produce AT1-aa." (PMID 26569331, 2015). "In the present study, we showed that the plasma levels of CRP, IL-6 and TNF-α were significantly increased in acute TAAD patients (before T6) compared to those in uncontrolled hypertension and healthy volunteers." (PMID 25592634, 2015). "A growing body of evidence indicates that hypertension is an inflammatory state wherein proinflammatory cytokines, such as tumour necrosis factor-alpha (TNF-α) and interleukin-6 (IL-6), contribute to the hypertensive effect." (PMID 26055622, 2015). "Finally, adipokines (leptin, adiponectin, ghrelin) as well as pro-inflammatory cytokines (TNF-α, IL-6 and IL-1), and neuropeptides (α-melanocyte-stimulating hormone and neuropeptide Y) have also been reported as further links between adipose tissue, OS and hypertension." (PMID 25548896, 2014). "Recent evidence suggests that hypertension is an inflammatory condition where various PICs such as TNF, IL-6 and IL-1β, both centrally and peripherally, have been shown to play an important role in the pathogenesis of hypertension." (PMID 23691105, 2013). "Our results demonstrate that activation of PPAR-α attenuates Ang II-induced hypertension through up-regulation of CYP4A and CYP2J and an attenuation of inflammatory markers such as plasma IL-6, renal MCP-1, renal expression of ICAM-1 and COX-2." (PMID 22848208, 2012). "In experimental models of hypertension, the inhibition of NF-kB prevented ANGII-induced expression of IL-6, VCAM-1 and MCP-1, thus attenuating the inflammatory damage caused by ANGII." (PMID 20462420, 2010). "Compared with participants with NGT (n = 440), those with DM(n = 253) were heavier, had greater central fat distribution, more elevated IL-6 and FPG levels as well as a higher percentage of hypertension." (PMID 20428239, 2010). "The main finding of this study is that elevated baseline levels of IL-6 are linked to long-term AVF failure, regardless of age, sex, and cardiovascular risk factors such as DM, hypertension, IHD, and PAD." (PMID 39860495, 2025). "In this context, an elevated IL-6/TNF-α ratio may act synergistically with dysregulated vasoactive pathways, amplifying vascular dysfunction and sustaining postoperative hypertension." (PMID 41010423, 2025). "Compared with the two groups, the HFpEF group presented significantly greater levels of IL-6, LP(b), NT-ProBNP, and Cr and lower levels of TC, LDL, and HDL, with notable incidences of hypertension (70%, p = 0.004), CAD (56.7%, p < 0.001), and DM (46.7%, p < 0.001)." (PMID 41195417, 2025). "In well-controlled hypertension, inflammatory markers, including TNF-α and IL-6, were comparable to those in normotensive subjects, suggesting that effective blood pressure management may normalize systemic inflammatory activity." (PMID 41440524, 2025). "IL-6 and MCP-1, secreted by T cells, activate inflammatory signaling pathways such as the JAK/STAT pathway, contributing to the chronic inflammation that exacerbates hypertension." (PMID 40079010, 2025).
Hypertension (continued). "For hypertension or CVD, TNFR1 mediated 74.2% of the positive association with IL-10 independent of IL-6, while IL-6 mediated 47.9% of the association independent of TNFR1." (PMID 41280118, 2025). "The potential mechanisms may include: oxidative stress and chronic inflammation: hypertension induces vascular endothelial damage, promoting pro-inflammatory cytokines (such as TNF-α, IL-6) and reactive oxygen species release." (PMID 41398846, 2025). "Additionally, other researchers revealed that serum levels of TGF-β and IL-6 significantly increased and decreased, respectively, in a group with CAD and hypertension compared to the control group." (PMID 40868095, 2025). "Furthermore, hypertension with hypercholesterolemia increased the expression of TNF-α, IL-6, and IL-1β levels in renal tissues and was inhibited by treatment with Egb761." (PMID 39065815, 2024). "Also, a recent article has disclosed higher levels of IL-6, TNF-α, and hs-CRP in uncomplicated hypertension." (PMID 37759223, 2023). "Hypertension in pregnancy and childbirth all lead to increased maternal TNF-α and IL-6 levels." (PMID 37312032, 2023). "Furthermore, genetic depletion of IL-6 prevents angiotensin II-induced hypertension indicating that control of angiotensin-induced hypertension may be modulated by preventing monocyte vascular adhesion and fine tuning of IL-6 release and signaling pathway activation." (PMID 37854465, 2023). "Furthermore, similar results were obtained in Dahl Salt-Sensitive (SS) rats during a 5-week HS intake, which led to hypertension, as well as increased mRNA levels of TNF-α, IL-6, and IL-1β." (PMID 37108475, 2023). "After adjusting for age, gender, body mass index, cardiovascular diseases, hypertension, chronic kidney diseases, respiratory diseases, and vaccination status in the multivariate model, NLR and IL-6 were predictors for ICU admittance (OR 1.228 and 1.028, respectively)." (PMID 37834356, 2023). "Moreover, abundant ROS and inflammatory factors, including IL-6 and tumor necrosis factor-α (TNF-α), contribute to comorbid hypertension and anxiety in rats." (PMID 37273529, 2023). "We hypothesized that a high-salt diet may increase serum levels of IL-6, IL-8, TNF-α, and Ang II to promote hypertension." (PMID 36925479, 2023). "We aimed to investigate whether the causal relationship between T1DM and CVDs could be mediated by hypertension, inflammation factors (CRP and IL-6), LDL, HDL, or apolipoprotein." (PMID 37659996, 2023). "Furthermore, IL-6 stimulates IL-17 production by inducing the polarization of CD4+ T cells, resulting in hypertension." (PMID 37273529, 2023). "For hypertension, we constructed a two-kidney and one-clip renovascular hypertensive (2K1C) mice model and found the expression of Smyd2 increased accompanied by upregulation of the senescence markers (p21, VCAM-1, and IL-6)." (PMID 36585926, 2022). "Further studies have shown that depletion of pro-inflammatory cytokines including interleukin-6 (IL-6) and tumor necrosis factor-alpha (TNF-α) ameliorates or prevents hypertension and related end-organ damage." (PMID 36620210, 2022). "There are few studies on the link between interleukin 6 and CAD on the patients with hypertension." (PMID 36518119, 2022). "These IsoLG-containing immune cells infiltrate the perivascular space and kidneys and secrete pro-inflammatory cytokines including IL-1β and IL-6 from the APCs and IFN-γ and IL-17A from the T cells, resulting in vascular and kidney dysfunction and ensuing hypertension." (PMID 36620210, 2022). "Previous research has shown that gut microbiota dysbiosis could promote T helper 17 (TH17) cell activation and stimulate the production of IL-6, IFN-γ, and IL-17A, resulting in hypertension." (PMID 35887270, 2022).
Hypertension (continued). "Our study found that elevated IL-6 levels on POD2 as well as smoking, drinking, hypertension, prolonged mechanical ventilation and ICU stay were all independent risk factors for PP and that IL-6 may be a promising biomarker with good diagnostic value." (PMID 35794529, 2022). "Our in vivo and in vitro results indicated that blocking VCAM-1 can effectively attenuate Ang II-induced hypertension and cardiac remodeling possibly by reducing VLA-4+ macrophage adhesion/migration and generation of IL-1β, IL6 and TNF-ɑ and ROS, as well as activation of multiple signaling pathway." (PMID 36467095, 2022). "Specifically, it has been demonstrated that IL-1β could upregulate many proinflammatory genes, including IL-6, IL-17 and IFN-γ, resulting in further tissue injury and inflammation related events, like hypertension and myocardial infarction." (PMID 36703963, 2022). "Magnesium acts as an allosteric activator for adenylate cyclase, Na/K-ATPase, and phospholipase C. Magnesium downregulates IL-1 alpha, IL-4, IL-6, IL-1 beta, Il-10, IL-12, TNF-alpha and several chemokines involved in hypertension, numerous immune-inflammatory pathways, and in adverse pregnancies." (PMID 38807919, 2022). "Recent studies have shown that interleukin-1beta, interleukin-6, and TNF- alpha are all elevated in high blood pressure, suggesting that these inflammatory markers may play a role in the pathogenesis of hypertension." (PMID 36164390, 2022). "ssociations were essentially not modified by further adjustment for current depressive episode, antidepressant use, history of CVD, hypertension, B vitamins (PLP, riboflavin) and low-grade inflammation (composite score of CRP, SAA, sICAM-1, IL-6, IL-8 and TNF-α)." (PMID 34409496, 2021). "However, it has already been reported that whey protein supplementation reduces pro-inflammatory cytokine IL-6 and tumor necrosis factor alpha (TNF-α) levels in patients with ischemic stroke, chronic obstructive pulmonary disease, and hypertension." (PMID 34858171, 2021). "All the pro-inflammatory biomarkers (IL-1β, IL-6, IL-8, and TNF-α) were positively correlated with the clinical parameters at baseline or following completed treatment, except for the PCR in subjects with hypertension." (PMID 34299815, 2021). "She had no gross hematuria, oliguria, edema, or hypertension, but further tests indicated a decreased glomerular filtration rate, hematuria, proteinuria, and an elevated level of IL-6." (PMID 34425760, 2021). "Since it is known that hypertension generally raises TNF-α, IL-1β, IL-6, HIF-1α, TGF-β, and VEGF mRNA and/or protein levels, the results obtained in the study may provide a positive prognostic factor for such activity in vivo." (PMID 33652665, 2021). "As hypertension generally raises TNF-α, IL-1β, IL-6, HIF-1α, TGF-β, and VEGF mRNA expression and/or protein levels, the results obtained in the studied model may provide a positive prognostic factor for such activity in vivo." (PMID 33652665, 2021). "Univariate logistic regression analysis showed that age, hypertension, SOFA score, and the levels of IL-6, WBC, NE, LYM, red blood cell, hs-CRP, DBIL, ALP, GGT, urea nitrogen, uric acid, cystatin C, sodium, chlorine, phosphorus and CK-MB were related to the aggravation of the patient's condition." (PMID 34397917, 2021). "BBR (1.25, 2.5, and 5 μmol/L) could inhibit the apoptosis of aortic endothelial cells isolated from SHR, decrease the expression of TLR4, MyD88, NF-κB, IL-6 and TNF-α, and have a certain protective effect on hypertension-induced vascular endothelial injury." (PMID 33815112, 2021). "IL-6 is considered a chief biomarker for cardiovascular risk in CKD with and without hypertension, and has been evaluated clinically in dialysis and non-dialysis patients." (PMID 33668632, 2021).
Hypertension (continued). "Prior research suggests that dysbiotic gut microbiome could promote TH17 cell activation and stimulate the release of IL-6, IL-17A, and IFN-γ, leading to hypertension." (PMID 34573025, 2021). "In general, among the patients with hypertension combined with CHF with preserved LVEF, the level of proinflammatory status indicators (CRP, TNF-α, IL-6) corresponded to the normative range of values; however, it was significantly higher in males than in females." (PMID 35366254, 2020). "Individuals with T2DM in combination with arterial hypertension exhibit maximum TIMP-1 levels and TIMP-1:MMP-2 and TIMP-1:MMP-9 ratios, as well as enhanced secretion of tumor necrosis factor alpha (TNF-α), interleukin-16 (IL-6), and IL-17." (PMID 33419373, 2020). "Compared with patients without ACI, patients who developed ACI were older, had more comorbidities (e.g. hypertension, DM, CHD, and COPD), lower readings of the lymphocyte count, eGFR and OOS, but higher readings of the leukocyte count, ALT, IL-6, hs-CRP, and NT-proBNP on admission (all P < 0.05)." (PMID 33235220, 2020). "The involvement of IL-6 was verified in the Ang-II-induced hypertension model, but not related to salt-sensitive hypertension." (PMID 32848763, 2020). "Studies using IL-6–/– mice showed that the absence of this interleukin promoted an attenuation in the hypertension induced by Ang-II infusion." (PMID 32848763, 2020). "In a model of hypertension and end-organ damage by angiotensin II or high salt induction, deletion of IL-6 failed to prevent the development of hypertension, but attenuated myocardial inflammation and fibrosis, leading to an improvement in cardiac function." (PMID 33171670, 2020). "Cytokines such as interleukin (IL)-6 and also MCP-1 may play a role in the development of arterial hypertension." (PMID 31655529, 2019). "Both SNPs genotypes were not significantly related to hypertension or to IL-6 and CRP plasma levels." (PMID 29495593, 2018). "All 3 viral miRNAs associated with combinations of inflammatory or prothrombotic circulating biomarkers (sTNFRII, IL-6, sICAM1, OPG, P-selectin) but did not associate with hypertension, coronary heart disease or cancer." (PMID 29686252, 2018). "Thus, the aim of this work was to determine the Th1/Th17 (IL-6, IL-2, TNF, IL-17 and IFN-γ) and Th2 (IL-4 and IL-10) serum profile in Venezuelan Chagasic patients stratified according amiodarone treatment, hypertension and arrhythmias." (PMID 28327099, 2017). "Some evidence suggests that cytokine levels are increased in human hypertension, and serum levels of inflammatory cytokines (IFN-γ, IL-6, and TNF-α) have been positively correlated with BP in humans; thus, they can act as the important biomarkers of low-grade systemic inflammation." (PMID 28910394, 2017). "An innovative study employing sgp130Fc (a soluble form of gp130 that binds IL-6/sIL-6R complexes and prevents them from signaling) inhibited the development of hypertension, but not vascular hypertrophy." (PMID 29186034, 2017). "In individual hypertension disorders, significantly lower levels of IL-6 and IL-13 were observed only in the GH group but not in PE and EC groups when compared with normal pregnant women." (PMID 28348564, 2017). "On the other hand it has been detected that levels of IL-6 in patients with hypertension with no history of systemic disease is higher and has a direct relationship with proportion of blood pressure." (PMID 28042549, 2017). "CRP level was a significant factor of the progression of hypertension in all models (P<0.001); apparently, TNF-α and IL-6 levels are not factors for progression of hypertension." (PMID 28837559, 2017). "As observed in previous cases of IL-6-producing pheochromocytoma our patient had no hypertension but had fever, microcytic and hypochromic anemia, thrombocytosis, hyperfibrinogenemia, and hypoalbuminemia, suggestive of a marked inflammatory status." (PMID 27579040, 2016).
Hypertension (continued). "The pro-inflammatory and pro-fibrotic responses in AngII-induced hypertension are likely not exclusive of each other given the reported interaction and feed-forward mechanisms of the two pathways, specifically of IL-6 and TGF-β." (PMID 26121471, 2015). "Nevertheless, those with abdominal obesity and hypertension exhibited a significant increase in levels of IL-6, regardless of MetS." (PMID 25329057, 2014). "Higher BMI and a history of hypertension remained predictive of CC FA in our study, but did not fully account for the IL-6-white matter relationship." (PMID 25188448, 2014). "IL-6 and IL-10 levels were slightly increased in T2DM patients with hypertension." (PMID 23762057, 2013). "Similarly, overweight and obese participants, as well as those with hypertension, had higher hs-CRP, IL-6 and TNF-α levels, compared to their respective normal weight and normotensive controls." (PMID 22769230, 2012). "In addition to the high concentration of IL-6, the generation of ROS by NADPH oxidase may be the basis of Ang II-induced hypertension, promoting cardiovascular damage and electrophysiological changes." (PMID 41592077, 2026). "We demonstrated that hypertension exacerbated Pb-induced neuroinflammation in the prefrontal cortex (PFC), hippocampus, and hypothalamus, as evidenced by increased levels of proinflammatory cytokines (IL-6 and TNF-α) and decreased levels of anti-inflammatory cytokines (CD206 and IL-10)." (PMID 39853035, 2025). "However, concomitant hypertension, hyperlipidaemia and steroids use were numerically higher in the anti-IL-6 bDMARDs group, although the differences were not statistically significant." (PMID 39698233, 2025). "Similarly to age, TNFR1, IL-6, and TNF-a collectively mediated 100% of the positive association between hypertension or CVD and IL-10, although none were significant independently." (PMID 41280118, 2025). "Additionally, elevated levels of inflammatory cytokines such as IL-6 and TNF-α may activate both the hypothalamic–pituitary–adrenal axis and the renin-angiotensin-aldosterone system, further promoting hypertension and cardiovascular pathology." (PMID 41323632, 2025). "IL-6-producing pheochromocytomas are well-documented and tend to present with fever, elevated inflammatory markers, anemia, and thrombocytosis, rather than the typical tachycardia/hypertension." (PMID 41357012, 2025). "Moreover, IL-6 and TNF-α also promote the production of RAAS components, especially angiotensinogen, further contributing to systemic and local angiotensin II formation and hypertension development." (PMID 37180779, 2023). "This might be because these rats had not yet reached the stage of hypertension; thus, the anti-inflammatory function of IL-6 is activated more to maintain homeostasis when the rats are young." (PMID 37375565, 2023). "Therefore, IL-6 may well have a potential therapeutic role in CVD treatment, especially with hypertension." (PMID 36703963, 2022). "Although the source of macrophages contributing to pro-inflammatory cytokine elevation in the kidneys of Ang II-dependent hypertension has not been identified, production of IL-6, a stimulus of proximal tubular AGT expression, has been demonstrated in kidney-resident macrophages." (PMID 35887028, 2022). "However, the associations of hypertension with lesions of a large number of immune factors including IL-17, MCP-1, IL-6, TGF-β, IL-10 and others have not been fully characterized." (PMID 36195874, 2022). "Interleukin‐5 (IL‐5), IL‐6 and IL‐12 levels correlated with mean CT in acute CSC (p = 0.008, p = 0.003 and p = 0.044, respectively), while IL‐8, IL‐6 and TNF‐α plasma levels correlated with hypertension in chronic CSC (p = 0.005, p = 0.033 and p = 0.001, respectively)." (PMID 32701204, 2021).